IGLV8-61 (immunoglobulin lambda variable 8-61)
Description:
V region of the variable domain of immunoglobulin light chains that participates in the antigen recognition. Immunoglobulins, also known as antibodies, are membrane-bound or secreted glycoproteins produced by B lymphocytes. In the recognition phase of humoral immunity, the membrane-bound immunoglobulins serve as receptors which, upon binding of a specific antigen, trigger the clonal expansion and differentiation of B lymphocytes into immunoglobulins-secreting plasma cells. Secreted immunoglobulins mediate the effector phase of humoral immunity, which results in the elimination of bound antigens. The antigen binding site is formed by the variable domain of one heavy chain, together with that of its associated light chain. Thus, each immunoglobulin has two antigen binding sites with remarkable affinity for a particular antigen. The variable domains are assembled by a process called V-(D)-J rearrangement and can then be subjected to somatic hypermutations which, after exposure to antigen and selection, allow affinity maturation for a particular antigen.
Synonyms: IGLV861; V3-4
Gene: Immunoglobulin variable (V) gene on chromosome 22 (22,098,700 to 22,099,212, forward strand). Ensembl gene ENSG00000211638.
Subcellular location: Secreted; Cell membrane
Gene Ontology:
Biological process: immune response
Cellular component: extracellular region; immunoglobulin complex; plasma membrane
Homologues: Paralogues in human: IGLV7-46 (60% identical), IGLV7-43 (59% identical), IGLV2-18 (53% identical), IGLV1-40 (52% identical), IGLV2-11 (52% identical), IGLV2-8 (51% identical), IGLV6-57 (51% identical), IGLV1-50 (50% identical), IGLV2-14 (50% identical), IGLV2-23 (50% identical), IGLV3-19 (50% identical), IGLV1-44 (49% identical), and 81 more.